EGFR (epidermal growth factor receptor)
Diseases named in the same sentence as EGFR in open-access papers (continued):
Sharing a sentence is not in itself a finding about the gene and the disease.
tumor (continued). "This is in accordance with its function as tumour suppressor in GBM by negatively regulating epidermal growth factor receptor (EGFR) and platelet-derived growth factor receptor beta (PDGFRB) genes." (PMID 33610185, 2021). "EFEMP1 exerts its tumor suppressor activity by suppression of tumor angiogenesis and inhibition of the EGFR/AKT signaling pathway." (PMID 33827418, 2021). "Unlike CALM1 that has been seldom reported in the setting of ESCC, studies of EGFR in tumor are relatively extensive." (PMID 33602237, 2021). "The EGFR, known as HER1, is from the ErbB group and is involved in diverse mechanisms, including invasion and dissemination of tumor cells." (PMID 34769090, 2021). "Historically, the search for novel therapies has focused on tumour cells, attempting to inhibit oncogenic pathways that drive tumour progression; targeting the EGFR pathway for example." (PMID 35048030, 2021). "The majority of TNBCs (>50%) are EGFR positive, yet individual tumor cells frequently display or develop resistance to EGFR inhibitors, and clinical trials of EGFR inhibitors in TNBC have been disappointing." (PMID 35052426, 2021). "The HDI romidepsin was able to improve erlotinib anti-tumour effect in nine NSCLC lines with varying histology and mutation conditions, including EGFR-, KRAS-mutant, and wild type cell lines, with a decrease in tumour load in NCI-H1299 xenograft models." (PMID 34769131, 2021). "The inhibition of EGFR-mediated signal transduction induced apoptosis, thereby evoking the initiation of anti-tumor immune responses." (PMID 34830971, 2021). "The programmed cell death 1 (PD-1) is expressed on activated T cells and programmed cell death ligand 1 (PD-L1) is upregulated on tumor cells possibly by activation of EGFR and PI3K-Akt or JAK/STAT pathways." (PMID 34298761, 2021). "For decision-making for either anti-VEGF or anti-EGFR therapy, both the mutational status (i.e., resistance to anti-EGFR treatment in RAS-mutant mCRC), and the tumor localization have to be appreciated." (PMID 34769209, 2021). "In CD-1 mice, the co-administration of a gelofusine and L-lysine decreased renal uptake and improved the tumor uptake of a 99mTc-labeled anti-EGFR Nb (7C12)." (PMID 34575943, 2021). "A retrospective study reported a conflicting result, i.e., concurrent upregulation of PD-L1 expression and tumor-infiltrating CD8+ T cells were rarely observed in EGFR-driven NSCLC." (PMID 34088360, 2021). "Additional predictors of pathological tumor response (TRG 1–3) were the administration of anti-VEGF or anti-EGFR therapies (OR = 9.748, p = 0.001, and OR = 69.830, p < 0.001, respectively) and metastasis size (OR = 0.961, p = 0.049)." (PMID 33530435, 2021). "EGFR signaling regulates tumor proliferation, progression, angiogenesis, evasion of apoptosis, and evasion of immunity." (PMID 34088360, 2021). "For MC-BR-BTY-0006, EGFR levels were lowest in its derived PDX tumor tissue, but highest for MC-BR-BTY-0019." (PMID 34145270, 2021). "Exposure to airborne contaminants, such as polycyclic aromatic hydrocarbons, can upregulate EREG expression through the EGFR signaling pathway, thereby promoting tumor progression." (PMID 34884633, 2021). "As oncology shifts towards precision medicine and personalized therapy, EGFR is an appealing therapeutic target in various cancer types due to its role in tumor growth and survival." (PMID 35601813, 2021). "A similar pattern is also seen with SHH inhibitors, as one study has shown that treating EGFR inhibitor-resistant HNSCC cells with the SHH inhibitor IPI-926 reduces tumor growth and blocks tumor recurrence in patient-derived HNSCC xenografts." (PMID 35048028, 2021). "Epidermal growth factor receptor (EGFR) signal activation in NSCLC cells contributes to tumor growth and impedance to apoptosis." (PMID 35582384, 2021).
tumor (continued). "Secreted SPINK1 proteins enhanced radioresistance of cancer cells even under normoxic conditions in EGFR-dependent and nuclear factor erythroid 2–related factor 2–dependent (Nrf2-dependent) manners and accelerated tumor growth after radiotherapy." (PMID 34747365, 2021). "Src and activated EGFR form a complex that synergistically promotes DNA synthesis, cell growth in soft agar and tumor formation in nude mice." (PMID 34638240, 2021). "For the tumor promoter genes SMAD6, TERT, EGFR, and PIK3CA, low levels of expression were associated with better survival, as expected." (PMID 33919332, 2021). "This supports the choice of FR-α as the CAR target and OV-mediated, tumor-directed delivery of EGFR-specific BiTEs to avoid systemic exposure." (PMID 33863363, 2021). "Based on these findings, it can be concluded that derivatives 3 and 11 are promising scaffolds for further modification and optimisation to obtain potent and selective anti-tumour agents with EGFR inhibitory activity." (PMID 34227457, 2021). "The most frequent genetic lesions in GB include the constitutive activation of phosphatidylinositol 3-kinase (PI3K) and Epidermal Growth Factor Receptor (EGFR) pathways, which drive cellular proliferation and tumor malignancy." (PMID 33513131, 2021). "Due to this tumor-specific feature, novel therapeutic agents are currently under development to target the overexpressed EGFR or EGFRvIII proteins." (PMID 33435537, 2021). "In GBM tumorigenicity, Tyr15 phosphorylation of CDK5 activated by EGFR phosphorylates TRIM59 at Ser308 to promote tumor growth." (PMID 35006426, 2021). "Upregulation of CREB protein can transform normal parenchymal cells into tumor cells through aberrant activation of downstream pathways, such as growth factor receptor (i.e., EGFR) and cytokine/JAK/STAT pathways." (PMID 34535664, 2021). "Nimotuzumab (NTZ), an EGFR-targeted drug, plays an anti-tumor role mainly by binding to the extracellular domain of EGFR and inhibiting EGF binding." (PMID 34578147, 2021). "The GPCR pathway regulates signal transduction and activates EGFR indirectly in cancer resulting in tumour progression and proliferation." (PMID 33991433, 2021). "Specific genomic features affecting the efficacy and resistance rate of anti-EGFR therapy should also be explored to demonstrate their relationship with primary tumour locations." (PMID 34188197, 2021). "An antibody that only binds overexpressed, mutants, or ligand‐activated forms of EGFR in cancer cells was identified by screening thousands of EGFR monoclonal antibodies for tumour specificity." (PMID 34694743, 2021). "In vivo cetuximab therapy was also ineffective on R521K harboring tumor xenografts, while blocked the tumor growth of EGFR-wild type xenografts." (PMID 34257586, 2021). "Various clinical studies support the notion that the efficacy of anti-EGFR antibodies is restricted to left-sided tumours." (PMID 34253874, 2021). "The boronate-mAb conjugate (BD-C225) demonstrated a specific accumulation in tumor cells expressing the EGFR in vitro." (PMID 33920126, 2021). "Further evidence of the involvement of the EV cargo in angiogenesis is based on the presence of EGFR in tumor-derived MVs." (PMID 34830787, 2021). "We found 6 hub genes in DEGs that overlapped with the tumor-related modules, and the overexpression level of B3GNT3 was significantly associated with the worse OS (overall survival) of the EGFR-MT LUAD patients (p < 0.05)." (PMID 34868228, 2021). "In 29 among 56 LUAD patients, EGFR expression was higher in tumor tissues than in normal tissues (red color of patients’ ID in tumor tissue)." (PMID 34503223, 2021). "AZD1480 is another JAK1/2 tyrosine kinase inhibitor that has shown promising anti-tumor efficacy in an EGFR-driven model of lung adenocarcinoma by inhibiting STAT3 signaling but lacked overall clinical activity in human NSCLC patients (NCT01219543)." (PMID 34944848, 2021).
tumor (continued). "We then continued to investigate the functional importance of EGFR in tumor cluster formation by genetic modulation of its expression levels." (PMID 33995681, 2021). "PD-1 inhibitors were found to inhibit tumor cell proliferation in coculture systems of EGFR-mutant tumor and immune cells in vitro." (PMID 34113560, 2021). "Overactivation of various signaling branches, for example, EGFR and HER, has been associated with the development of epithelial malignancies promoting tumor growth, invasion, and metastasis." (PMID 33207034, 2021). "The effects of cetuximab on EGFR activation were more obvious in EGFR-high tumor tissues than in EGFR-low tumor tissues." (PMID 32989241, 2021). "Patients with EGFR-amplified tumours exhibited a similar trend for worse PFS and OS also when survival analysis was conducted by treatment arm." (PMID 33199443, 2021). "Our in vitro data are strongly supported by in vivo results, which show that G1 significantly inhibits tumor growth of HCC xenografts through the GPER/EGFR/ERK axis, and that the specific activation of the GPER/ERK pathway notably enhances tumor reduction." (PMID 33767999, 2021). "We next assessed mutant EGFR and total MET transcript expression in a series of EGFR-mutant patient tumor specimens through quantitative RT-ddPCR." (PMID 34516823, 2021). "In summary, this research group identified a loop between the tumour and stromal component of metastases, formed by TNFα-TGFα-EGFR." (PMID 33671588, 2021). "DRD2 and EGFR have been found to synergistically promote GBM tumors growth, and a combined inhibition of both DRD2 and EGFR causes a synergistic tumor-killing effect in mouse GBM." (PMID 34503167, 2021). "Our in-vivo data shows that anti-EGFR/VEGFR2 BsAb had a better inhibitory activity in controlling the growth of tumor xenografts bearing MDA-MB-231 cells in comparison to single targeting mAb treatment alone." (PMID 33804477, 2021). "In a phase I/II clinical study (NCT01869166) at the Chinese PLA General Hospital, advanced NSCLC patients with over 50% EGFR-positive expression on tumor cells received anti-EGFR CAR-T-cell therapy." (PMID 33025047, 2021). "The link between EGFR and DSB repair suggests strategies to modulate tumor radiosensitivity by inhibiting NHEJ indirectly with available drugs that target EGFR and AKT1/3 pathways." (PMID 34337349, 2021). "Treatment-naïve primary tumor tissues paired with the acquired EGFR TKI-resistant tumor tissues were collected from 9 NSCLC patients and were subjected to IHC staining with an anti-SGLT1 antibody." (PMID 34155348, 2021). "Studies addressing the anti-tumor potency of quinazolin derivatives have established anti-proliferative and anti-angiogenic properties by their ability to target epidermal growth factor receptor and platelet derived growth factor receptor." (PMID 34280220, 2021). "Patients with metastatic NPC whose EGFR expression in the tumor was lower than grade 3 had significantly better survival outcomes than did those with grade 3 expression (p = 0.008)." (PMID 34204797, 2021). "Alterations in the EGFR gene have been found to be involved in cancer cell growth and tumor vascularization." (PMID 34439273, 2021). "By expanding the quantities of samples, further results were obtained showing that CALM1 and EGFR-positive staining is positively correlated with tumor progression and poor overall prognosis." (PMID 33602237, 2021). "These EGFR‐directed NK cells showed enhanced in vitro cytotoxicity, and their intracranial injection in an orthotopic mouse model resulted in improved tumor control and increased survival." (PMID 33959279, 2021). "Overall, however, our study shows that under normal conditions, CPAP exerts tumor preventive function in OSCC through promoting the homeostasis of EGFR and suppressing EMT." (PMID 33889303, 2021).
tumor (continued). "In the AOM/DSS model, EGFR signaling acts as a tumor suppressor by stimulating mucosal regeneration, thereby limiting the duration of the inflammatory response." (PMID 33976143, 2021). "In this model, ablation of RAF1 or EGFR caused a delay of the formation of PDAC, whereas the concomitant knock-out of both RAF1 and EGFR genes completely suppressed tumour development." (PMID 33920182, 2021). "No objective responses were noted in the 11 patients treated with erlotinib and onalespib (10 EGFRex20ins and one EGFR E19del), although half of the patients (5/10) with EGFRex20ins treated with erlotinib and onalespib had some degree of tumor shrinkage." (PMID 34140248, 2021). "Multi-region and temporal sequencing of tumor tissue during the course of the third-generation epidermal growth factor receptor (EGFR) tyrosine kinase inhibitor (TKI) osimertinib has identified significant heterogeneity in resistance mechanisms." (PMID 34283064, 2021). "Cetuximab, an EGFR inhibitor, was used as a fluorescently labeled dye delivered at the time of surgery as an intraoperative guide to improve tumor resection." (PMID 33919596, 2021). "We showed that protein restriction combined with the EGFR inhibitor afatinib reduced tumor growth and normalized life span." (PMID 34766923, 2021). "A panel of tumor-derived extracellular vesicle markers, including EGFR, EPCAM, HER2, MUC, GPC1, WNT2, and GRP94, was investigated." (PMID 33803470, 2021). "Overexpressed ILT4 in EGFR-activated tumor cells induced TAM recruitment and M2-like polarization, which impaired T cell function." (PMID 33537094, 2021). "The therapeutics has radio- and chemo-toxicity simultaneously and specifically target to EGFR-expression tumor cells, thereby achieving synergistic anticancer activity." (PMID 33672989, 2021). "More importantly, poor water solubility and insufficient accumulation of EGFR inhibitors at the tumor site limit their application." (PMID 34322025, 2021). "For example, several tumor antigens that have been used for targeted therapies in human cancers are also identified in canine malignancies, including EGFR, HER2, VEGFR2, CD20, podoplanin, PD-1, and PD-L1." (PMID 34944112, 2021). "GBOs retain the originating tumor heterogeneity to a high degree out beyond 12 weeks of culturing and maintain the expression of endogenous EGFR and its alterations, providing a valuable model platform for testing therapies aimed at addressing tumor escape." (PMID 34568006, 2021). "Our work also has established much needed preclinical modeling for T cell–mediated immunotherapy in RMS and identified EGFR-based immunotherapies as a new approach to kill RMS tumor cells." (PMID 34415995, 2021). "EGFR modifications are believed to have a role in tumor invasiveness (regulating proliferation and motility of tumor cells) and often occur in the infiltrating periphery of GBM, accounting for the fuzzier appearance of tumor margins." (PMID 33498680, 2021). "In this review, we provide new insight into EGFR therapeutic resistance in the tumour microenvironment (TME) and summarize current agents for the TME." (PMID 34663410, 2021). "Activation of EGFR inhibits the apoptotic system in tumor cells and promotes tumor cell proliferation, angiogenesis and metastasis." (PMID 34788230, 2021). "Studies have revealed that EGFR plays a role in regulating the tumor immune microenvironment and immune response." (PMID 34566988, 2021). "Drug resistance caused by oncogene mutations or activation of oncogenic signaling pathways and increased tumor plasticity is the major obstacle encountered in the application of target therapies such as anti-EGFR therapy." (PMID 34884633, 2021).
tumor (continued). "Conjugation of RBCEVs with α‐EGFR VHH also increased the percentage of CFSE‐positive tumour cells to ∼20% in the targeted α‐EGFR‐RBCEV treatment." (PMID 33643546, 2021). "In CRC, EGFR is highly expressed and is closely related to the clinicopathological stage of the tumor, the extent of lymph node involvement, vascular infiltration, and tumor distant metastasis status." (PMID 34733314, 2021). "In previous work, we have demonstrated that the expression of EGFR is downregulated in diffusion-limited, hypoxic areas of the tumor microenvironment of HNSCCs." (PMID 33718186, 2021). "For P3 and P8, who only had progressive tumor and CTC samples, the driver genes EGFR with p.L858R mutation and LEF1 of the Wnt signaling pathway were detected, respectively, in both CTCs and progressive tumors of each patient." (PMID 34616428, 2021). "One study observed that SQI reflects the VAF of the EGFR mutant allele obtained by NGS methods and that dynamic changes in SQI reflect the tumor progression." (PMID 34441254, 2021). "Four years later, the tumor relapsed as a right hilar mass and was identified as EGFR wild-type through histological samples; the patient then received radiotherapy and chemotherapy." (PMID 33828971, 2021). "In our xenograft study, we used human ramucirumab, therefore it is unlikely that ramucirumab arm of anti-EGFR/VEGFR2 BsAb mediated angiogenesis inhibition to suppress the growth of tumor xenografts in our study." (PMID 33804477, 2021). "We and others have previously shown that EphA2 controls NSCLC cell survival, cell death, migration and response to EGFR-TKI or VEGFR2-targeting on tumor cells." (PMID 33671073, 2021). "Antibody-receptor complexes are then internalised and degraded, leading to EGFR down-regulation on the surface of tumour cells." (PMID 34069119, 2021). "The skin metastasis sample showed a very similar pattern of alterations in driver genes as compared with the treated tumor, including the PIK3CA hotspot mutation, the amplifications in CCND1, EGFR, and FGFR3, and the deletions in CDK1B, CDKN2A, and CDKN2B." (PMID 34680239, 2021). "Regarding its mechanism of action, UBE3C induces the proteasomal degradation of Annexin A7: this protein is believed to act as a tumor suppressor in GBM via attenuation of the epidermal growth factor receptor (EGFR) signaling." (PMID 33665742, 2021). "A major signaling pathway contributing to tumor cell resistance is the PI3K/AKT signal pathway activated through EGFR." (PMID 33919702, 2021). "High affinity of necitumumab, a fully humanized mAb, for EGFR inhibits phosphorylation of the EGFR and subsequent downstream signaling, leading to inhibition of tumor cell proliferation and tumor growth." (PMID 33522929, 2021). "Plasma RAS status in circulating tumor DNA (ctDNA) is gaining attention as a novel predictive biomarker for the efficacy of rechallenging anti-EGFR mAbs." (PMID 34098908, 2021). "The anti-EGFR/VEGFR2 BsAb described here demonstrates anti-tumor activity in TNBC cells including MDA-MB-231 cells which harbor KRAS mutation." (PMID 33804477, 2021). "Among patients receiving anti-EGFR-based therapies, 23 (34%) had a RAS and BRAF wild-type tumour, while a RAS or BRAF mutation was found in 16 (23%) and 6 (9%) cases, respectively." (PMID 33024268, 2021). "The suppression of the PI3K/AKT/mTOR signaling pathway can induce autophagy, which in turn saves tumor cells from the harm of epidermal growth factor receptor (EGFR)-tyrosine kinase inhibitors (TKIs)." (PMID 34336650, 2021). "In some studies, tumour heterogeneity, mutations in RAS and the mAb binding sites have been associated with resistance to anti-EGFR mAbs in patients with mCRC." (PMID 33562755, 2021). "Upregulated AXL and its interaction with EGFR were associated with resistance to PI3Kα inhibition due to sustained mTOR activation, and addition of AXL inhibitor R428 sensitized tumor cells to PI3Kα." (PMID 34830794, 2021).